YAP1 (Yes1 associated transcriptional regulator)
Diseases named in the same sentence as YAP1 in open-access papers (continued):
Sharing a sentence is not in itself a finding about the gene and the disease.
tumor (950 papers, 2007 to 2026). "We examined the association of TGFβ3/GLI2/YAP1 with tumor infiltration of various immune and immunosuppressive cells." (PMID 40027190, 2025). "The aberrant upregulation of Yes-associated protein 1 (YAP1) in a variety of solid cancers contributes to tumor progression and poor clinical outcomes, rendering it an appealing therapeutic target." (PMID 39827153, 2025). "The elevated expression and activity of YAP1, a pivotal downstream effector of the Hippo pathway, are associated with tumor growth, metastasis, therapy resistance, and poor prognosis in various human cancers, including HCC." (PMID 40307228, 2025). "Mechanistic studies have shown that CLDN6 promotes tumor progression via the CLDN6/tight junction protein 2 (TJP2)/yes-associated protein 1 (YAP1) axis, activating the Hippo signaling pathway." (PMID 41425250, 2025). "Yes-associated protein 1 (YAP1), a core effector of the Hippo pathway, is involved in tumor progression." (PMID 40626009, 2025). "YAP1 has been implicated in tumor progression of a variety of human cancers, which renders it an appealing therapeutic target." (PMID 39827153, 2025). "YAP1, a potent transcriptional coactivator and a key downstream effector of Hippo pathway, is implicated in tumor pathogenesis and is frequently activated in various cancers including HCC." (PMID 40307228, 2025). "YAP1 also correlates positively with favorable immune biomarkers, such as tumor mutation burden (TMB) and infiltration of CD8+ T, NK, and Th1 cells." (PMID 40977060, 2025). "In BC, elevated expression of YAP1 can activate tumor-associated fibroblasts (CAFs), prompting them to secrete a variety of tumor-promoting factors, including TGF-β and VEGF." (PMID 40388100, 2025). "The lncRNA MIR4435-2HG increases tumor growth and metastasis formation by sponging miR-206 that regulates the Yes-associated protein 1 (YAP1) transcription factor, a major effector and downstream regulator of the Hippo pathway." (PMID 40535722, 2025). "In leukemia, particularly with FLT3-ITD mutations, YAP1 levels are reduced, and restoring its expression can delay tumor progression." (PMID 41479777, 2025). "Using phosphoFAK (pFAK) as a readout for ECM-integrin engagement, we found that loss of pFAK in tumor cells was highly correlated with reduced nuclear YAP1 staining and gain of ASCL expression as measured by multiplex immunofluorescence (p<0.005)." (PMID 41509338, 2025). "YAP1 (Yes-associated protein 1) is a transcriptional regulator involved in cancer progression, acting as both an oncogene and a tumor suppressor." (PMID 41479777, 2025). "Higher YAP1 expression was associated with poorer tumor differentiation and higher staging in both groups (p < 0.05)." (PMID 40191726, 2025). "Conversely, loss of Ser41 phosphorylation by CDK4/6 inhibition or Ser41A mutation, promotes YAP1 degradation and suppresses YAP1‐driven tumor progression." (PMID 39968498, 2025). "In CRC, nuclear accumulation of unphosphorylated YAP1 has been associated with advanced tumor stage, lymph node metastasis, and resistance to chemotherapy, underscoring its clinical relevance." (PMID 40872562, 2025). "The role of the YAP1-induced IL-6–associated signaling cascade in regulating the tumor microenvironment (TME) has been poorly understood, particularly in UCB." (PMID 39630608, 2024). "YAP1 (Yes1-associated transcriptional regulator) is a transcriptional coactivator that fuels several hallmarks of cancer 5, including tumor initiation, cell plasticity, drug resistance and metastasis." (PMID 38169595, 2024). "Increased yes-associated protein 1 (YAP1) levels are present in the surrounding tumor tissue in clinical PCa samples with a high Gleason grade and are positively associated with metastasis and poor prognosis." (PMID 39092186, 2024). "Deficiency or inhibition of YAP1 enhances the killing ability of T cells and NK cells to tumor cells." (PMID 38550587, 2024).
tumor (continued). "Analysis of RNA-Seq data of mouse UCB cell lines with varied levels of YAP1 expression indicated a possible YAP1-driven enrichment of signaling pathways associated with tumorigenesis and tumor immune evasion." (PMID 39630608, 2024). "Yap1, a key regulator of tissue growth and homeostasis, has been linked to several aspects of tumour stemness and growth." (PMID 38659080, 2024). "These distinct YAP1-driven mechanisms underlying macrophage recruitment highlight a context-dependent tumor-macrophage symbiosis and the need for developing personalized medicine to target this symbiosis." (PMID 38443336, 2024). "In line with this, Yap1-deficient macrophages in cKO mice show increased susceptibility to ID8-derived tumor growth and metastasis, attributing to a higher M2-like/M1-like macrophage ratio and decreased CD8+ T cell infiltration in the ascites and omentum." (PMID 39198883, 2024). "NAT10 drives tumor progression and lymphangiogenesis by facilitating the nuclear import of the Yes1‐associated transcriptional regulator (YAP1)." (PMID 39640362, 2024). "Our data identifies the transcriptional effector YAP1 as impacting tumor-intrinsic gene expression in STK11-deficient, KRAS-driven human LUAD cell lines." (PMID 37968341, 2024). "High expression of Yes1-associated transcription regulator (YAP1) in PDAC tumor cells indicates poor prognosis, whereas ubiquitination and degradation of YAP1 reduce the expression of gal-9, inhibit M2 polarization of TAMs, and thus suppress immune escape." (PMID 40458305, 2024). "We suggest that LTB4R2 activation by 12-HHTrE produced by aHSC CYP1B1 causes CTNNB1 activation via GSK3β pathway and subsequent YAP1 transcription and tumor promotion." (PMID 37156770, 2023). "YAP1-2γ contains a γ fragment encoded by an alternative exon 6 and exhibits significant anti-tumor activity by enhancing CCL2 expression and attracting massive macrophage infiltration." (PMID 37416784, 2023). "Yes-associated protein 1 (YAP1), a transcriptional coactivator of Hippo signaling, plays a pivotal role in tumor proliferation, metastasis, and chemoresistance." (PMID 37709768, 2023). "The tumor suppressor effect of TPM2 was associated with blocking YAP1 nuclear translocation and thus leading to its inactivation." (PMID 36823643, 2023). "To rule out the possibility that such results were caused by the nonspecific effects of LyzMCre, we adoptively transferred wild-type or Yap1/Taz-deficient neutrophils into wild-type tumor-bearing mice." (PMID 36921037, 2023). "In line with our findings, SRC-mediated YAP1 activation through direct phosphorylation has been implicated in many cancer progressions and tumor microenvironment regulation." (PMID 36633714, 2023). "The oncoprotein Yes-associated protein 1 (YAP1) is targeted by miR-375 and can be inactivated via the Hippo tumor suppressor pathway." (PMID 38505381, 2023). "NEX-Cre–mediated deletion of the other two members of the NDR kinase family, LATS1 and LATS2, causes YAP1 activation and tumour formation in brain." (PMID 36446521, 2023). "YAP1 (yes-associated protein 1), as a transcriptional coactivator of pro-proliferation and pro-tumor genes, is a main downstream effector of the Hippo pathway." (PMID 36941685, 2023). "Roles of SRSF3 in anti-tumor immune response can be exemplified by YAP1 (Yes-associated protein 1), an oncogenic co-transactivator." (PMID 37416784, 2023). "Various studies showed that CCR5 overexpression is also positively associated with tumor immune cell infiltration via the activation of effector T-cells and tumor suppressor genes, and repression of YAP1 oncogenic pathways." (PMID 37174125, 2023). "Another scRNA-seq study revealed that Yes-associated protein 1 (YAP1) was highly upregulated in peritoneal carcinomatosis (PC) tumor cells, conferred CSC properties, and appeared to function as a metastasis driver." (PMID 37612741, 2023).
tumor (continued). "MT3 regulates drug resistance in tumor cells by regulating the expression of YAP1, a protein that has been linked to tumor proliferation, invasion, and migration." (PMID 38041044, 2023). "Activation of YAP1 promotes cell proliferation and differentiation and has been implicated in tumor growth." (PMID 37345153, 2023). "YAP1 is a transcriptional co-activator whose abnormal regulation is implicated in tumor progression and therapy resistance." (PMID 38065955, 2023). "Mutations in many of the tumor suppressors upstream of YAP1/TAZ are common in a variety of cancer types." (PMID 35170430, 2022). "It is interesting to note that YAP1 is a critical downstream effector along the Hippo signaling implicated in carcinogenesis and malignant phenotypes, as well as resistance to anti-tumor therapies." (PMID 36182943, 2022). "Yes-associated protein 1 (YAP1), a central component of the Hippo pathway, plays an important role in tumor metastasis; however, the underlying mechanism remains to be elucidated." (PMID 35773411, 2022). "Yes-associated protein 1 (YAP1) functions as a tumor-promoting gene in multiple cancers, and ectopic expression of YAP1 promotes oncogenic transformation." (PMID 35864972, 2022). "On the other hand, when both tumors and THP-1 cells are both present in culture, Yap-1 silencing suppressed oncogenic pathways as well as tumor infiltration by tumor-associated macrophages." (PMID 36467420, 2022). "As a master regulator of EMT 22, the abnormal expression of yes-associated protein 1 (YAP1) promotes malignant tumor proliferation and metastasis, induces EMT and cause drug resistance 22, 34-36." (PMID 36147462, 2022). "Interesting, it has been previously shown that activation of YAP-1 in cancer cells, contributes to many oncogenic-associated mechanotransduction signaling pathways, including tumor initiation, progression, and metastasis." (PMID 35662260, 2022). "TEAD-dependent YAP1 function has also been linked to invasive and metastatic behavior of tumor cells." (PMID 36479120, 2022). "This study shed light on the underlying mechanism and novel pathways involving YAP1 in the development of distant tumor metastasis in anti-angiogenesis regimens and suggested novel targets to improve the long-term effectiveness of anti-angiogenesis treatment." (PMID 36591473, 2022). "Whole genome analysis demonstrated that ZEB1-mediated activating protein-1 (AP-1) and Yes1 Associated Transcription Regulator (YAP1) activate tumor-promoting genes to induce aggressive breast cancer types." (PMID 35743249, 2022). "In view of these, we assessed the association between YAP1 expression and tumor cell proliferation in pan-cancer." (PMID 35685435, 2022). "Yes-associated protein 1 (YAP1) has been proven to function as a key modulator in tumor cell proliferation, metastasis, and stem cell activity since it was first identified in 1994." (PMID 36428672, 2022). "The abnormal expression of YAP1 is associated with the proliferation and invasion of various tumor cells." (PMID 35911146, 2022). "The shortlisted target genes that showed significant concordance with YAP1 expression were further analyzed for association with aggressive clinical parameters such as high grade, larger tumor size, later stage and lymph node positivity." (PMID 35407556, 2022). "Accordingly, co-upregulations of LIN28 and MSI2 in TNBC tissues were strongly associated with YAP1 protein level and tumor malignance." (PMID 35102250, 2022). "Taken together, these data highlight the positive association of high tumor stromal content of TME with the expression of YAP1 and induction of EMT and metastasis." (PMID 34680267, 2021).
tumor (continued). "Loss of YAP1 in epithelial cells also reduced the number of tumor promoting cancer‐associated fibroblasts and lymphocytes in early stage lesions, suggesting that YAP1 influences KRAS‐mediated tumor progression through multiple mechanisms." (PMID 34003553, 2021). "In human cells, overexpression of SHANK2 also caused sustained YAP1 activity even at high cell density and promoted tumor formation in mice." (PMID 34150758, 2021). "Defects in Hippo pathways that included RASSF7 amplification and NF2 or LATS1/2 mutations were present in 50% of tumours and were accompanied by micromolar responses to the YAP1 inhibitor Verteporfin." (PMID 34580349, 2021). "The loss of YAP1 in S462 cells decreased colony formation in soft agar and tumor formation in the S462 xenograft model." (PMID 33808166, 2021). "High nuclear YAP1 expression was associated with aggressive tumor features, including hormone receptor negativity, high HG, lymph node metastasis, and high Ki67 expression." (PMID 33718163, 2021). "The predominant cytoplasmic YAP1 was observed in patients with CS-CCA associated with tumor metastasis in our current study." (PMID 35201494, 2021). "Overexpression of YAP1 and its activation (nuclear localization) are associated with poor prognosis in several tumor types, including gastric adenocarcinoma (GAC)." (PMID 33588867, 2021). "Rescue experiments showed that overexpression of YAP1 reverses the tumour inhibitory effect caused by IMUP knockdown." (PMID 33094920, 2020). "Yorkie (Yki), the Drosophila ortholog of the Yes-Associated Protein 1 (YAP1), acts as a transcriptional cofactor that mediates the effects of the Hippo tumor suppressor pathway." (PMID 32737120, 2020). "We tested if deficiency in YAP1 phosphoregulation by LATS1/2 is sufficient to cause tumour formation by conditionally knocking out Lats1 and Lats2, in NEX-Cre lineage." (PMID 32404936, 2020). "In many human malignancies, upregulation of YAP1 is reported to be associated with enhanced cell growth, tumor formation, and worse clinical outcomes." (PMID 32894161, 2020). "In the Hippo signalling cascade, the HPV E6 directly binds with the Yes-associated protein (YAP1) to initiate and accelerate tumour progression in cervical oncogenesis." (PMID 33076322, 2020). "YES‐associated protein 1 (YAP1) plays a key role as a transcriptional coactivator in the Hippo tumor suppressor pathway." (PMID 30868052, 2019). "In this model, tumor growth is closely associated with an increase in the nuclear expression of YAP1 and β-catenin." (PMID 31511432, 2019). "More importantly, since the combinatorial treatment showed inhibition of YAP1, we expect these drugs to show efficacy in K-Ras-independent PDAC tumors, where YAP1 is known to compromise for the loss of K-Ras to promote tumor growth." (PMID 31100813, 2019). "Overexpression or overactivation of YAP1 has been associated with tumor progression and worse survival in multiple cancers." (PMID 30824765, 2019). "Mutation of the TEAD binding site in the YAP1 fusion or repression of NFI targets prevents tumor induction in mice." (PMID 31477715, 2019). "A functional association of high nuclear DUSP10 levels with nuclear YAP1 expression was also observed in tumor cells of CRC patient samples." (PMID 31717606, 2019). "Yes-associated protein 1 (YAP1) is an effector of Hippo pathway, which plays a significant role in cell proliferation and tumor progression." (PMID 30539010, 2018). "The pivotal role of YAP1 in oncogenesis is highlighted by its association with the Hippo pathway, which is characterized as tumor suppressive in various cancers." (PMID 30214681, 2018). "We enrolled 46 tumors from surgically resected patients with NSCLC who had received TKI therapy to examine the possibility of an association between the expression of PD-L1 and YAP1 and with tumor response to TKI therapy in these patients." (PMID 29435131, 2018).
tumor (continued). "A recent study of patients with TNBC showed that YAP1 expression in tumor cells and the surrounding stroma is associated with a decreased likelihood to achieve pathological complete response (pCR)." (PMID 29228705, 2017). "In this study, we investigated the role of YAP1 in promoting colon tumorigenesis in tumor cells and association with M2 TAM polarization." (PMID 28241877, 2017). "Sulforaphane suppresses ECS cell tumor formation and this is associated with reduced levels of YAP1 and ∆Np63α." (PMID 29088716, 2017). "The YES-associated protein (YAP1) transcription coactivator has been implicated as an oncogene and is amplified in human cancers and provides tumor cells strong proliferation and survival cues." (PMID 29163769, 2017). "Wild-type RB1 mutation status, used as a surrogate marker of YAP1 expression, was prognostic for decreased patient survival and increased chemo-refractory tumor response." (PMID 29088741, 2017). "The findings also illustrated that YAP1 expression was associated with higher tumor grade in patients with TNBC, further highlighting the role and the relevance of YAP1 in the pathology of TNBC." (PMID 29228705, 2017). "In these cancers, high YAP1 expression is associated with tumor initiation, invasion and metastasis, suggesting that YAP1 promotes tumorigenesis." (PMID 28036290, 2017). "Dysregulation of CSC signaling like Hippo/YAP1, Wnt/β-catenin, and hedgehog (Hh) have been implicated in the maintenance of tumor and in conferring therapy resistance." (PMID 26317542, 2015). "In ER- tumours the relationship is reversed and high YAP1 expression was linked to more aggressive features." (PMID 24559095, 2014). "Taken together, in ER+ tumours low YAP1 expression is linked to more clinically aggressive features including grade and proliferation." (PMID 24559095, 2014). "This is in support of our results where strong YAP1 expression was associated with increased proliferation in ER- tumours." (PMID 24559095, 2014). "Notably, the tumor-specific increased levels of Tyrosine-protein kinase Fyn and Yes1-associated transcriptional regulator (YAP1) signaling suggest molecular drivers of radioresistance." (PMID 42193055, 2026). "Yes-associated protein 1 (YAP1) is a critical regulator/factor in HCC tumor progression." (PMID 40918140, 2025). "GAS5 overexpression has also been demonstrated to repress endometrial cancer formation in immunodeficient mice models through PTEN/AKT signaling and directly repressing oncogenic yes-associated protein 1 (YAP1) in tumor-associated macrophages, transforming them into an anti-tumor phenotype." (PMID 39941145, 2025). "Aberrant nuclear localization of YAP/TAZ—often driven by high-frequency genomic events such as FAT1 loss, WWTR1 amplification and YAP1 amplification—correlates with increased tumor proliferation, metastasis, chemoresistance and significantly shorter overall and progression-free survival." (PMID 40486910, 2025). "Moreover, the N6-methyladenosine (m6A) modification of LATS2, a critical component of the Hippo pathway, has been implicated in tumor progression by suppressing ferroptosis through the YAP1/ATF4/PSAT1 axis." (PMID 40136353, 2025). "Immune evasion and tumor progression result from CircYAP1's direct binding to the YAP1 (yes1 associated transcriptional regulator) protein, which inhibits its phosphorylation and increases YAP1 nuclear import." (PMID 40453757, 2025). "Nuclear YAP1 is linked to poor prognosis and increased tumor aggressiveness." (PMID 40895190, 2025). "N-acetyltransferase 10 (NAT10)-ankyrin repeat and zinc finger peptidyl tRNA hydrolase 1 (ANKZF1) axis promotes tumor progression and lymphangiogenesis of ccRCC by enhancing the nuclear import of Yes1-associated transcriptional regulator (YAP1), and upregulating expression of VEGF-C/-D." (PMID 41511312, 2025).